ALK (ALK receptor tyrosine kinase)
Diseases named in the same sentence as ALK in open-access papers (continued):
Sharing a sentence is not in itself a finding about the gene and the disease.
lung cancer (continued). "More recently, a retrospective study demonstrated that patients with ALK fusion-positive lung cancers have improved response rate and progression-free survival when treated with either pemetrexed monotherapy or combination therapy." (PMID 26316937, 2012). "Recent studies have shown in the lung cancers with mutant PIK3CA, there are also mutations at other driver oncogenes, such as EGFR, KRAS, BRAF, MEK, and anaplastic lymphoma kinase (ALK)." (PMID 23006971, 2012). "A series of other fusion partners with the intracellular ALK portion were discovered thereafter, most recently as a transforming oncogene in a small subset of lung cancers." (PMID 23267434, 2012). "For example, presence of the fusion protein EML4-ALK has been found to define histologically-distinct subsets of lung cancer, and ALK-positive anaplastic large cell lymphomas (ALCL) appear to have a better prognosis than ALK-negative ALCLs." (PMID 22347506, 2012). "Our findings in this study identified one more partner gene that should be targeted in ALK-fusion detection using RT-PCR in lung cancer." (PMID 22347464, 2012). "The first reported data came from the phase I study (1001), published in a New England Journal of Medicine article in 2010: an interim analysis of 82 ALK-positive lung cancer patients treated with crizotinib." (PMID 25031935, 2012). "Early-phase clinical trials have revealed that TKIs that target ALK show marked efficacy in patients with lung cancer positive for EML4–ALK." (PMID 22240786, 2012). "In this study, we examined the frequency and patterns of ALK rearrangements in clinical specimens from a large cohort of lung cancer patients from both primary and tertiary settings across the United States referred for molecular profiling." (PMID 23198868, 2012). "Lung cancer patients with ALK rearrangements have been shown to have significant reductions in tumor burden in response to treatment with the ALK inhibitor crizotinib, which led to its accelerated FDA approval in the United States in 2011." (PMID 23198868, 2012). "Based on these initial results, an international phase III trial randomizing patients with advanced lung cancer harboring ALK fusions to crizotinib versus standard chemotherapy after disease progression on first-line treatment is now ongoing." (PMID 26316937, 2012). "In a large unselected series, the frequency of ALK gene rearrangement detected by FISH was approximately 3.5% of lung carcinoma, and 3.7% of patients with lung adenocarcinoma, with variant signal patterns frequently detected." (PMID 23198868, 2012). "Recently, a novel highly sensitive antibody allowed for the routine detection of ALK-rearranged lung carcinomas by standard IHC." (PMID 21444946, 2011). "The anaplastic lymphoma kinase (ALK) gene is frequently involved in translocations that lead to gene fusions in a variety of human malignancies, including lymphoma and lung cancer." (PMID 20624322, 2010). "Future studies will explore the potential correlation of SH2 binding patterns with activation of other RTKs implicated in lung cancer, such as IGFR, FGFR, PDGFR, ALK, and EPH receptors." (PMID 20976048, 2010). "Careful review of the literature reveals that ALK fusion proteins are frequently present in lung cancer patients." (PMID 20624322, 2010). "Targeting cytoskeletal remodeling and adherens junction dynamics may provide a novel therapeutic approach to overcome drug resistance in metastatic ALK-rearranged lung cancer." (PMID 41679471, 2026). "This knowledge may not only help the audience understand the basics of the biology of ALK‐positive lung cancer, but also have an impact on decision‐making and treatment management thereby contributing to improved healthcare outcomes." (PMID 41213866, 2025). "Consequently, increasing attention has been directed toward the management of ALK-targeted drug resistance in lung cancer." (PMID 40873540, 2025).
lung cancer (continued). "For advanced ALK+ lung cancer, European Society of Medical Oncology (ESMO) and NCCN guidelines recommend all three generations of ALK inhibitors such as alectinib, brigatinib and lorlatinib, noting significant improvement in PFS with second- and third-generation agents." (PMID 40439365, 2025). "In lung cancers resistant to ALK-targeted drugs, tumor cells may achieve immune escape via several pathways: First, they may downregulate the expression of tumor antigens, reducing immune system recognition and attack." (PMID 40873540, 2025). "Consequently, overcoming bypass resistance requires a deeper mechanistic understanding of signaling networks in lung cancer, which will inform the development of novel therapeutic strategies and improve the long-term efficacy of ALK-targeted treatments." (PMID 40873540, 2025). "Anaplastic lymphoma kinase (ALK) is a potent oncogenic driver in lung cancer." (PMID 41190033, 2025). "The second hypothesis suggests that SCLC transformation can occur in ALK inhibitor-treated lung cancers or in wild-type EGFR or ALK NSCLC treated with immunotherapy; however, the exact mechanism remains unclear." (PMID 40248195, 2025). "In our study, we observed that ORR and DCR were not affected by EGFR mutation-positive, ALK-positive, and ROS-1-positive in patients with advanced lung cancer who received camrelizumab-based therapies." (PMID 40124372, 2025). "This also applies to ALK inhibitors used in the treatment of lung cancer and ALCL." (PMID 40073758, 2025). "Additionally, this case revealed the presence of an EML4 (exon 6):: ALK (exon 20) (V3) fusion, which was one of the most common genetic alterations observed in lung cancer." (PMID 40224190, 2025). "Taken together, understanding the complex interactions between ALK-targeted therapy and the immune microenvironment is crucial for developing more effective treatment approaches and improving clinical outcomes in patients with lung cancer." (PMID 40873540, 2025). "This article summarizes current knowledge of the mechanisms of resistance to ALK-targeted therapy in lung cancer, including both primary and acquired mechanisms, treatment strategies following resistance, recent therapeutic advances, and the impact of the immune system and tumor microenvironment." (PMID 40873540, 2025). "Among the 23 lung cancer-associated genes, gene fusions were detected in 2 samples: one with EML4-ALK fusion and another with ALK-unknown gene fusion." (PMID 40948762, 2025). "We encountered an ALK-positive lung cancer patient who responded well to pembrolizumab." (PMID 40660550, 2025). "Therefore, despite its high cost and the complex detection procedure, NGS-based assays are achieving broad applications in detecting ALK rearrangements of lung cancer patients." (PMID 40853979, 2025). "The progress in precision medicine, with Epidermal Growth Factor Receptor (EGFR) inhibitors, Anaplastic Lymphoma Kinase (ALK) inhibitors, and immune checkpoint inhibitors, has significantly improved survival and quality of life for patients with advanced lung cancer." (PMID 40452440, 2025). "In general, ctDNA-based ALK detection may perform better in patients with advanced lung cancer, with high clinical utility." (PMID 40853979, 2025). "Targeted therapy is an important method in the treatment of lung cancer, especially in the detection of common NSCLC mutations such as epidermal growth factor receptor (EGFR), rat sarcoma viral oncogene (KRAS), anaplastic lymphoma kinase (ALK), and BRAF genes." (PMID 39962757, 2025). "Small intestine metastasis in ALK-rearrangement lung cancer is infrequent." (PMID 40224190, 2025). "The signaling pathway of the ALK fusion protein promotes the survival and migration of tumor cells, meaning ALK (+) lung cancer may be more prone to lymph node and distant metastasis and present at a higher clinical stage." (PMID 40083024, 2025). "As a result, ALK has become another critical target in the treatment landscape of lung cancer." (PMID 41282618, 2025).
lung cancer (continued). "This review has been written with the intention of explaining to the patients with ALK‐positive lung cancer, and to their families, friends, carers and medical teams, in simple terms, the fundamentals, and the current state of knowledge of this particular type of cancer." (PMID 41213866, 2025). "For example, German health care claims do not include any information regarding the histological lung cancer subtype as well as PD-L1 expression of the tumor or other genetic mutations such as EGFR or ALK." (PMID 40739492, 2025). "In this model, EGFR or anaplastic lymphoma kinase (ALK) gene alterations, Karnofsky performance status (KPS) score, and the presence or absence of extracranial metastases are independent risk factors for the prognosis of LMs of lung cancer." (PMID 40484812, 2025). "Moreover, ceritinib also displayed activity against lung cancer cell lines that are resistant to alectinib, a third-generation ALK inhibitor, suggesting a broader mechanism of action for ceritinib not involving the ALK receptor." (PMID 40968384, 2025). "Additionally, the prevalence of ALK fusion was 9.4%, which is higher than the overall frequency (5.1%) reported in a prospective study of Chinese lung cancer patients." (PMID 39707836, 2025). "Patients with ALK+ lung cancer often seek second opinions from major cancer centers to access subspecialized expertise and novel investigational therapies, which may facilitate the development of more personalized treatment plans." (PMID 40674592, 2025). "Notably, the introduction of second-generation drugs in this class, such as alectinib and brigatinib, along with third-generation lorlatinib, has expanded treatment options for ALK-mutant lung cancer, surpassing the previous use of crizotinib." (PMID 41293380, 2025). "Therefore, it is essential to determine the exact ALK status in lung cancer patients, in an effort to choose the optimal therapy and suitable surveillance plan." (PMID 40853979, 2025). "This study indicates that ZYY-B-2 may be a potential therapeutic to overcome ALK rearrangement-positive lung cancer cell resistance to ceritinib." (PMID 40584293, 2025). "Genomic studies have identified driver mutations associated with primary lung cancer, including epidermal growth factor receptor (EGFR), anaplastic lymphoma kinase (ALK), ROS1 Proto-Oncogene Tyrosine Kinase Receptor (ROS1) and Serine/Threonine-Protein Kinase BRAF (BRAF)." (PMID 40492223, 2025). "Although the elevated levels of 15‐PGDH and STING1 have not been previously associated with ALK alterations, both proteins have been implicated in other genetic mutations in lung cancer." (PMID 40621945, 2025). "Also, it has been reported that the detection of various breakpoints and fusion partners of ALK gene fusions from blood samples in lung cancer patients is clinically useful." (PMID 40647546, 2025). "Among TKIs, ALK inhibitors have achieved the longest survival in patients on systemic treatment for advanced lung cancer, with a median OS exceeding 80 months, even with the presence of severe predictive and prognostic factors at baseline, such as brain metastases or aggressive co-mutations." (PMID 39796163, 2025). "The advent of ALK-targeted therapy has significantly improved survival rates in lung cancer." (PMID 40873540, 2025). "In this study, we did not discuss the impact of kinship status on EGFR-mutated or ALK-mutated lung cancers." (PMID 38721224, 2024).
lung cancer (continued). "This discovery led to the development of drugs targeting mTOR (e.g., everolimus and temsirolimus) and EGFR-TKIs targeting EGFR and ALK (e.g., ositinib, gefitinib, ceritinib, and loratinib), which have demonstrated clinical efficacy in the treatment of lung cancer." (PMID 39391313, 2024). "If ALK‐positive lung cancer can be predicted by tumor markers, such as CYFRA21‐1 positivity and the CYFRA21‐1:CEA ratio, we could prioritize the singleplex test for the ALK fusion gene at the initial stages of treatment." (PMID 38400801, 2024). "The management of lung cancer (LC) requires the analysis of a diverse spectrum of molecular targets, including kinase activating mutations in EGFR, ERBB2 (HER2), BRAF and MET oncogenes, KRAS G12C substitutions, and ALK, ROS1, RET and NTRK1-3 gene fusions." (PMID 38966170, 2024). "The treatment of ALK-positive NSCLC has shifted the treatment paradigm within lung cancer." (PMID 38835344, 2024). "Although CD155 was not significantly correlated with PD-L1 expression in the entire population, CD155high was associated with higher PD-L1 positivity in the oncogene-mutated subsets (ALK and EGFR alterations), which is concordant with studies in early-stage lung cancer." (PMID 39267111, 2024). "In addition, vaccines targeting mutated self-antigens such as KRASG12D and mutated anaplastic lymphoma kinase (ALK) have had some success, e.g. in patients with ALK-rearranged lung cancer." (PMID 38223410, 2024). "Besides providing a novel cancer model to support basic research on ALK-positive lung cancer, PDT-LUAD#119 lung tumoroids will help elucidate the pathogenesis of adenosquamous carcinoma." (PMID 38829559, 2024). "Similarly, anaplastic lymphoma kinase (ALK) rearrangements, more commonly targeted in lung cancer, have rarely been noted in CRC." (PMID 38672633, 2024). "The advent of molecular targeted therapies, particularly those targeting receptor tyrosine kinases in advanced NSCLC (e.g., mutations in the epidermal growth factor receptor [EGFR] or anaplastic lymphoma kinase [ALK] genes), has revolutionized lung cancer treatment." (PMID 39230026, 2024). "Emerging evidence has revealed that in addition to EGFR TKI therapy failure, AST has also been observed in other molecular targeted therapy resistance of lung cancer, e.g. in lung cancer patients who have relapsed from ALK inhibitor treatment or KrasG12C inhibitor adagrasib treatment." (PMID 39687207, 2024). "Conversely, ALK has been proposed as a potential biomarker for favorable prognosis in lung cancer." (PMID 39123462, 2024). "In addition, telomerase reverse transcriptase (TERT), a gene localizes on 5p15.33, has been found to amplify in 4.6% of anaplastic lymphoma kinase positive (ALK+) lung cancer patients." (PMID 38242874, 2024). "In addition, another group of researchers established ALK+ lung cancer cell lines resistant to ceritinib." (PMID 38397899, 2024). "Peer-reviewed articles from the last ten years were selected using the combination of the following keywords: “lung cancer genetics”, “targeted therapy lung cancer”, “EGFR mutations”, “ALK rearrangements”, and “immune checkpoint inhibitors”, without any restriction." (PMID 39199653, 2024). "This trend may be attributable to the different mutation rates of genes such as EGFR, ALK, and KRAS in younger versus older lung cancer patients." (PMID 38568892, 2024). "However, a subgroup of lung cancers relies on the ALK for survival, and treatment with the ALK inhibitor crizotinib initially yields remarkable tumor responses." (PMID 38397899, 2024). "Five patients had ALK+ lung cancer, four of them with brain metastases." (PMID 38610927, 2024). "This discrepancy excluded some patients from the study cohort that may have been eligible if the inclusion criteria had been broader to incorporate all patients with lung cancer receiving ALK TKIs from any database." (PMID 39851929, 2024).
lung cancer (continued). "In a more recent study, molecular tests (EGFR and/or ALK activating mutations, and/or ROS1 rearrangements, and/or PD-L1 expression) were performed in 40% of patients with stage III lung cancer and 60% of those with stage IV lung cancer in the Dolnośląskie voivodeship in 2019–2020." (PMID 39518907, 2024). "The potential role of alternative ADCs targeting the human trophoblast cell‐surface antigen 2 (TROP2) (NCT04152499) and MET351, 352 (NCT03859752) is also being evaluated in patients with lung cancers, potentially including NSCLCs with EGFR mutations or ALK rearrangements." (PMID 39184861, 2024). "In lung cancer, meningeal carcinomatosis is frequently associated with adenocarcinoma histotype, oncogenic driver mutations like epidermal growth factor receptor (EGFR) mutation, and anaplastic lymphoma kinase (ALK) translocation." (PMID 38921299, 2024). "In a previous study conducted by the University of California Lung Cancer Consortium, 54.9% of patients had EGFR mutations, 32.9% of patients had KRAS mutations, 5.3% of patients had ALK fusions, and < 3% of patients had other mutations (HER2, MET, RET, ROS1, or BRAF-non-V600E)." (PMID 39009968, 2024). "Notably, young lung cancer patients often harbor a higher frequency of driver mutations, including epidermal growth factor receptor (EGFR) and anaplastic lymphoma kinase (ALK) translocations." (PMID 38946288, 2024). "Other less common rearrangements detected in lung cancer patients include KIF5B-ALK (kinesin family member 5B-ALK), TFG (trafficking from ER to golgi regulator)-ALK, KLC1 (kinesin light chain-1)-ALK, PTPN3 (protein tyrosine phosphatase non-receptor type 3)-ALK, STRN (striatin)-ALK." (PMID 39457620, 2024). "Also, there is a lack of evaluation of TF concentration in peripheral blood of lung cancer patients in the current study, limited by the fact that the number of enrolled ALK-rearranged NSCLC patients is too small." (PMID 37940761, 2024). "Diagnostics of lung cancer, including ALK-positive lung cancer, are still developing." (PMID 39457620, 2024). "Furthermore, transformation into SCLC can occur in anaplastic lymphoma kinase (ALK)-positive lung cancer upon treatment with ALK-inhibitors and in wild-type EGFR or ALK NSCLC following immunotherapy." (PMID 38395864, 2024). "However, in the present study, 36% of ALK‐positive lung cancer patients were unexpectedly CYFRA21‐1‐positive." (PMID 38400801, 2024). "The ALK (anaplastic lymphoma kinase) in Lung Cancer Trial of Brigatinib in 1st Line (ALTA-1L) was a randomized, open-label, controlled, phase 3 study evaluating the efficacy of brigatinib (experimental arm) versus crizotinib (control arm) on Progression-Free Survival (PFS)." (PMID 39707229, 2024). "However, two patients with ALK-rearranged lung cancer, previously treated with multiple ALK-TKIs and other therapies, showed promising outcomes when treated with a combination of bevacizumab and lorlatinib." (PMID 38397899, 2024). "However, divergent findings from another investigation suggest that initial PD-L1 levels do not significantly forecast the success of alectinib therapy in individuals with ALK-positive lung cancer." (PMID 38835380, 2024). "Another retrospective study from 2021 with 83 patients diagnosed with ALK-positive lung cancer mostly treated with single-agent immunotherapy described a median time to treatment discontinuation of 2.17 months, an outcome that is consistent with our pre-ABCP experience." (PMID 38610927, 2024). "In addition, lung cancers, including the ALK‐positive non‐small‐cell and RET Fusion‐positive variations, constituted about 9% (2/23) of the studies." (PMID 38984669, 2024). "In addition, among patients with ALK fusion-positive lung cancer who had progressed on ALK TKIs, YES1 amplification was detected in 2 of 17 samples." (PMID 38338729, 2024).